JAK1 (Janus kinase 1)
Diseases named in the same sentence as JAK1 in open-access papers (continued):
Sharing a sentence is not in itself a finding about the gene and the disease.
tumor (continued). "HPV-positive tumors showed unique deletions of tumor suppressors such as NTRK1 and JAK1." (PMID 37461056, 2023). "This sequential cascade amplifies the translation of Jak1 mRNA and fosters the phosphorylation of STAT3, thereby facilitating immune‐suppressive functionalities in these myeloid cells and mediating mechanisms for tumor immune evasion." (PMID 38034101, 2023). "In addition, DOK7 overexpression also reduced the levels of p-JAK1, p-JAK2 and p-JAK3 in the tumor tissues." (PMID 38095644, 2023). "Furthermore, Ruxolitinib, a JAK1/2 inhibitor, was able to overcome chemoresistance and to improve survival in the immunocompetent OC mouse model system using ID8 tumor cells and MSCs, alongside a decrease in pSTAT3 levels." (PMID 37175439, 2023). "Non-clinical efficacy and PK/PD studies of golidocitinib (also named as AZD4205 or DZD4205) in xenograft model allow for increased and longer suppression of JAK1/STAT3 signaling and subsequent better anti-tumor activity as compared to ruxolitinib (Jason G. 7, 8)." (PMID 37077916, 2023). "These JAK1 frameshift mutations have previously been described as recurrent mutations and non-functional mutations, especially in dMMR/MSI-H tumours and have been associated with resistance to ICI if complete loss of function occurs." (PMID 36870947, 2023). "Moreover, the accretion of lactate within the tumor microenvironment has been shown to instigate histone H3K18 lactylation, engendering elevated expression of Mettl3 and m6A modification of Jak1 mRNA within tumor‐infiltrating myeloid cells." (PMID 38034101, 2023). "We also detected five mutations (ALOX2B, JAK1, PGR, RUNX1, SOX1) in the HGSOC41.1 tumor sample but not in the corresponding PDO." (PMID 37202753, 2023). "Furthermore, our results may allow us to test whether engineering the IFN-γR/JAK1/STAT1 signaling pathway in APCs could be of value in achieving a more efficient presentation of endogenous tumor–associated peptides to CD4+ T cells and potentially enhancing tumor responses." (PMID 36445781, 2023). "To determine whether the activation is specific to JAK inhibition by ruxolitinib, we treated BMDMs with CM from 4T1 tumor cells in presence of Solcitinib and NVP-BSK805, inhibitors specific for JAK1 and JAK2 respectively." (PMID 37005447, 2023). "IL‐13 activates the IL‐13 receptor complex to elicit signaling of the JAK1/STAT6 pathway, which may promote cell differentiation and inhibit tumor growth." (PMID 36806727, 2023). "TRP-1 CD4+ T cells also locally clustered at the invasive margin of MHC-deficient HCmel12 Jak1-KO tumours, whereas Pmel-1 CD8+ T cells only infiltrated the invasive margin but not the tumour centre." (PMID 37316667, 2023). "Adverse events with JAK1 inhibition combined with either IDO1 or PI3Kδ inhibition were manageable, but the combinations demonstrated limited clinical activity or enhancement of immune activation in the tumor microenvironment." (PMID 35288468, 2022). "IFN-γ is mainly produced by T cells, NK cells and NK T cells, and IFN-γ signal must be activated through JAK1/2/STAT1 pathway, suggesting that IFN-γ/JAK1/2/STAT1 pathway may be involved in anti-tumor immune response." (PMID 35740594, 2022). "By contrast, MITF, CCR7, JAK1, ELN, and SLC6A4 were lowly expressed in tumor tissues." (PMID 36425071, 2022). "STAT3 knockdown abolished osteoclast- or IL-19–induced STAT3 phosphorylation in tumor cells, but did not affect upstream JAK1 phosphorylation." (PMID 36006737, 2022). "In addition to JAK1 inhibition (itacitinib) having independent activity in HCC827 xenograft model, synergistic tumor growth inhibition was also observed in combination with erlotinib or osimertinib." (PMID 34773474, 2022). "Therefore, IL-6 can affect the stability of PD-L1 and its binding to PD-1 on immune cells through the IL-6/JAK1/STAT3 pathway, thereby mediating the immune escape of tumor cells." (PMID 34568032, 2021).
tumor (continued). "The tumor-suppressive role of TCPTP in T-ALLs is attributed to its capacity to attenuate oncogenic protein tyrosine kinase signalling, including that mediated by JAK1, and the aberrant fusion protein NUP214-ABL1." (PMID 34884538, 2021). "The hexatherapy regimen induced robust IFN-γ production in peripheral CD8+ T cells and promoted not only vaccine antigen-specific T cells but also T cells specific for the endogenous retroviral tumor antigen gp70 (p15E and AH1) and neoepitopes (Jak1 and Ptgfr)." (PMID 33602696, 2021). "Finally, in human NCI-H292 tumor epithelial cells, IFN-γ activates phospholipase C-γ (possibly via an upstream tyrosine kinase distinct from JAK1/JAK2) which induces the sequential activation of PKC-α c-Src and STAT1." (PMID 33668421, 2021). "We investigated JAK1 and STAT1 protein expression levels in macrophages from CTRL and Co-CM1 groups and found that their expression was inhibited in macrophages co-cultured with tumor cells." (PMID 33937269, 2021). "Importantly, Tris DBA downmodulated the expression of activated JAK1, JAK2, and STAT3, and Ki-67 in MM tumor tissues." (PMID 34771643, 2021). "The overall survival time for patients with EGFR‐amplified tumours exhibiting increased levels of phosphorylated JAK1 was significantly shortened compared with patients with tumours negative for one or both features." (PMID 33523587, 2021). "Surprisingly, our data are in contradiction to the described observations as we do not observe anti-tumour effects of JAK1/2 inhibition on cell proliferation." (PMID 32046095, 2020). "Another study revealed that leptin provoked the JAK1/2, STAT3, FAK, ERK, and GSK3αβ signaling cascade to stimulate the production of soluble ICAM-1 in cancer cells, which induced osteoclast formation and enhanced tumor-induced osteolysis in vivo." (PMID 33371368, 2020). "Besides attenuating JAK1/2 activation, OMT also inhibited c-Src phosphorylation involved in STAT5 activation in tumor cells." (PMID 30621055, 2019). "Indeed, JAK1 and JAK2 were activated/phosphorylated in tumor cells of lung AC patients as determined by a pathologist (H.P.)." (PMID 31407334, 2019). "Additionally, the results from western blot assays revealed that knockdown of HE4 obviously inhibited expression of p-JAK1, p-JAK2 and p-STAT3 in xenograft tumor tissues." (PMID 31477564, 2019). "In addition, PHS-based inhibition of EMT was attributable to the downregulation of the EGFR/JAK1/STAT3 signaling axis, as validated by immunoprecipitation assays and breast tumorigenesis mice models." (PMID 29100426, 2017). "Based on these data, we speculate that JAK1 frameshift alterations and the resultant unresponsiveness to IFN lead to reduced anti-tumor immune responses." (PMID 29121062, 2017). "Here, using both in vitro and in vivo colon carcinoma models, we found that fasting could suppress M2 polarization of TAMs through inactivating JAK1/STAT3 in the tumor microenvironment and therefore inhibit tumor cell growth." (PMID 29088814, 2017). "Instead of a dysfunctional glucocorticoid-induced transcriptional response, Meijerink and colleagues identified aberrant activation of specific signaling pathways downstream of mutant IL7R, JAK1 or NRAS, or wild-type AKT as major determinants of steroid resistance in the isogenic tumor lines." (PMID 27997538, 2016). "No significant anti-tumor activity of ruxolitinib was observed in rest three JAK1-mutant models, as well as JAK1-WT model." (PMID 26701727, 2016). "Indeed, the JAK1 inhibitor ruxolitinib, the MEK inhibitor CI1040, and the AKT inhibitor MK2206 were able to reverse steroid resistance in specific isogenic tumor lines." (PMID 27997538, 2016). "Taking into account the cases of the WES cohort and the additional eight cases with targeted sequencing, interestingly, the two tumours with no alterations in SETD2 (case 13 and case 6) both harboured concurrent mutations in JAK1 and JAK3." (PMID 27600764, 2016).
tumor (continued). "We next examined whether BSN either alone or in combination with paclitaxel inhibits p-JAK1, p-JAK2, and p-Src in NSCLC tumor tissues." (PMID 25788267, 2015). "In contrast to previous studies where resveratrol enhanced the function of tumour suppressor PTEN and inhibited activated Akt in tumour cells, resveratrol treatment in this study did not affect expression of JAK1, PTEN, TYK2 and Akt." (PMID 23372833, 2013). "Our data indicates that high expression of JAK1 correlates with favourable clinical outcome in ESFT, and it suggests that at least in some patients an advantageous acute inflammatory reaction is ongoing in tumour tissue." (PMID 22084725, 2011). "We also observed that tumor cells that engaged senescence-related transcriptional programs, or “Sen-High” cells, upregulated IFN-γ signaling machinery, including Ifngr1, Ifngr2, Jak1, Jak2, Irf1, and Stat1, as well as IFN-γ target genes Cxcl9, Cxcl10, and Tap1." (PMID 40299790, 2025). "In addition, IL6 is also crucial for the progression and metastasis of HCC through the activation of Janus kinase-1 (JAK1) and its downstream signal transducer and activator of transcription (STAT), which directly stimulate the proliferation, migration, and invasion of tumor cells." (PMID 39744421, 2025). "However, the absence of B2m, Jak1 or LMP2 expression on EMT6 tumor cells did not impact the frequency of macrophages, effector CD4+ or CD8+ T cells, or Tregs in the TME." (PMID 38427670, 2024). "Finally, we observe changes in JAK1 and TNF-α in tumor tissues by immunohistochemistry." (PMID 38379418, 2024). "Intriguingly, we found that PD‐L1 antibody monotherapy could induce phosphorylation of JAK1 and STAT3, thereby up‐regulating the expression of IRF1 and PD‐L1 in tumor tissues, which may also be one of the reasons why many patients are insensitive or resistant to PD‐L1 antibody monotherapy." (PMID 38953362, 2024). "In addition, loss of expression of tumor cells B2m and LMP2, but not Jak1, led to a significant decrease of polymorphonuclear myeloid-derived suppressor cells (PMN-MDSC) infiltrates in the TME." (PMID 38427670, 2024). "The impaired JAK1 and JAK2 activity was associated with a loss in the capability of IFN-γ to induce growth arrest and apoptosis and enhance immunogenicity mediated by the lack of APM induction in tumor cells." (PMID 37047709, 2023). "Similar frequencies of JAK1, JAK2, and STAT3 genotypes were seen in patients stratified by age, phototype, nevi presence, sun exposure, sunburn episodes, type of sun exposure, tumor location, ulceration, type of growth, Clark level, Breslow thickness, clinical stage, and metastases." (PMID 35982955, 2022). "Likewise, the medium and high doses of TAM significantly decreased the expression of p-JAK1 and p-STAT6 in the tumor tissues compared to that of the untreated control group, and the effect was stronger than that of TMZ, as detected by Western blotting and immune histology chemistry (IHC)." (PMID 35269804, 2022). "In our clinical study, JAK1 inhibition combined with either IDO1 or PI3Kδ inhibition did not lead to enhanced immune activation as evidenced by a lack of CD8+ T-effector cell infiltration into the tumor microenvironment." (PMID 35288468, 2022). "Furthermore, the low expression of MIR4435-2HG in MKN45 cell-derived exosomes inhibited the Jagged1/Notch and JAK1/STAT3 pathways in macrophages; MIR4435-2HG downregulated exosomes were found to significantly inhibit GC tumor growth in vivo by establishing a mouse model." (PMID 36483041, 2022). "We do not propose STAT3 or JAK1/2 inhibition as promising therapies to be combined with opioids, as this could result in severe immunosuppression or altered stromal-tumor cell signaling." (PMID 33465556, 2021).
tumor (continued). "Momelotinib competes with JAK1/2 for ATP binding, which may result in inhibition of JAK1/2 activation, inhibition of the JAK-STAT signaling pathway, and so the induction of apoptosis and a reduction of tumor cell proliferation in JAK1/2-expressing tumor cells." (PMID 34199353, 2021). "M1 subtype macrophages differentiate through mainly JAK1/2, STAT1/2, 5, TLR4/NF-κB, P38 MAPK pathway activation, excrete inflammatory cytokines and chemokines, participate in a positive immune response; as such, they are able to kill tumor cells in tumor tissue and foreign pathogens." (PMID 32850623, 2020). "IFN-γ produced by T cells upon tumor antigen recognition signals through IFN-γ receptor and consequently results in expression of IFN-γ stimulated genes by inducing activation of Janus kinase JAK1/2, and phosphorylation of the signal transducers and activators of transcription (STAT)." (PMID 32793604, 2020). "Indeed, a review of exome sequencing data (N = 2078 CRCs from cbioportal) showed a high prevalence of JAK1/2 mutations, but not of STAT5, in hypermutated tumours." (PMID 30670049, 2019). "While we did not observe a significant effect of JAK1 deficiency on IFNγ-mediated upregulation of MHC I in our model, JAK1 was shown to be required for expression of MHC II that can mediate tumor and self-antigen presentation in non-professional antigen presenting cells." (PMID 31552026, 2019). "Using JAK1/2-KOs cell lines we showed that intratumoral administration of the TLR-9 agonist SD-101 was able to overcome local resistance to anti-PD-1 even in abscopal sites, and the NKTR-214 overcame resistance to anti-PD-1 in the B2M-KO tumor growth and significantly increased survival." (PMID 30400822, 2018). "Blockade of JAK1/STAT3 signal pathway by knocking down STAT3 significantly weakened M2 polarization of RAW264.7 macrophages induced by adenosine in coculture condition and suppressed proliferation of CT26 cells, which further confirmed the effect of TAMs on tumor growth." (PMID 29088814, 2017). "Another inhibitor of JAK1 and STAT3, a synthetic triterpenoid, bardoxolone methyl (C-28 methyl ester of 2-cyano-3,12-dioxooleana-1,9,-dien-28-oic acid, also known as CDDO-Me) abrogated the immune suppressive effect of MDSCs on CD8+ cytotoxic T-cells resulting in decreased tumor growth in mice." (PMID 27886105, 2016). "Although JAK1/STAT3 mutants are oncogenic, they require lymphokine engagement (i.e. IL-6, IL-23) and JAK activation, whose inhibition (Ruxolitinib, HSP90) leads to STAT3 dephosphorylation, cell growth inhibition and lymphoma control in a Patient Derived Tumor Xenografted (PDTX) model." (PMID 26501073, 2015). "To test whether inhibition of the JAK/STAT3 pathway would affect the growth of pediatric solid tumors, we evaluated the anti-tumor activity of AZD1480, an ATP competitive inhibitor of JAK1 and JAK2, which has been shown to decrease the growth of adult tumors in several pre-clinical models." (PMID 23531921, 2013). "Indeed, pharmacological inhibition of IAP re-establishes JAK1-regulated Stimulator of interferon genes (STING) expression and DNA sensing signaling, enhances cytotoxic immune cell infiltration, and augmentes immune-dependent anti-tumor activity in an LKB1-mutant immune-competent mouse model." (PMID 40057483, 2025). "Finally, an overexpression of this miR leads to a reduced JAK1, STAT6, and AKT phosphorylation and IL-4-induced migration and invasion; this, together with data from the literature, leads to the conclusion that miR-494-5p is an early tumor and initial metastasis suppressor in CRC." (PMID 38201452, 2023). "A potential explanation for occurrence of infections upon JAK1/2-TKI administration and the overall lack of clinical activity of JAK1/2-TKIs might be that JAK1/2 inhibition reduces abundance and function of NK cells, thereby impairing defense against pathogens and anti-tumor immunity." (PMID 32365499, 2020).
tumor (continued). "Therefore, overexpression of JAK1 may not correspond to activation of the JAK/STAT signaling pathway in cancer cells but rather to the presence of mast cells within the tumor microenvironment." (PMID 32275708, 2020). "Importantly, treatment of JAK1 inhibitor in KP mice significantly downregulated the mRNA levels of Ccl7 in the lungs at 8 weeks after tumor induction, suggesting that CCL7 is upregulated in the tumor-burdened lungs in KP mouse model in a JAK-STAT-dependent manner." (PMID 33257678, 2020). "Consistently, JAK1 and MHC-I were markedly upregulated in tumor cells, but not in the macrophages, by TAK-243 administration." (PMID 39540840, 2025). "As expected, fedratinib and CHZ868 did not diminish the anti-tumor effect of CAR-T cells, likely due to their minimal effects on JAK1/3." (PMID 39891728, 2025). "Compared to wt tumors, the absence of B2m, Jak1 and LMP2 expression on tumor cells resulted in a significant reduction of monocytic myeloid-derived suppressor cells (M-MDSC) in the TME." (PMID 38427670, 2024). "Treatment with the potent JAK1/JAK2‐specific inhibitor, ruxolitinib, significantly reduces tumor burden; however, ruxolitinib treatment does not fully eradicate the malignant clone." (PMID 38104968, 2024). "The absence of B2m, Jak1 and LMP2 expression on EMT6 tumor cells did not impact the infiltration of macrophages, effector CD4+ or CD8+ T cells, or CD4+ regulatory T cells (Tregs)." (PMID 38427670, 2024). "Compared to wt EMT6, the absence of B2m or LMP2 protein expression on tumor cells resulted in a significant reduction of M-MDSCs and PMN-MDSCs in the TME, with Jak1 deletion only decreasing the former." (PMID 38427670, 2024). "Thus, the enrichment of JAK1 truncating frameshift mutations in dMMR/MSI EC at least partly explains their lack of IFNγ response, and may also partly explain the absence of a prognostic benefit of MMR loss in this tumour type." (PMID 35262923, 2022). "In a separate experiment, similar effects on tumor growth were obtained for a combination of INCB053914 with ruxolitinib, showing that JAK1-selective and JAK1/2 dual inhibitors behave similarly in these models (data not shown)." (PMID 29927999, 2018). "This concern is supported by a recent report showing that in vivo treatment with ruxolitinib did not suppress tumor growth and progression due to the abrogation of antitumor CD8+ T cell function through ruxolitinib-mediated inhibition of JAK1/2-dependent IFNGR1 signaling in T cells." (PMID 38236642, 2024). "Consequently, JAK–STAT activation, in a JAK1/JAK2- and STAT1/STAT3-dependent manner, is required for the transition to a stem-like, multilineage and EMT state but not for the tumor cells that have completely redifferentiated to an NE-like lineage." (PMID 36065066, 2022). "Therefore, the inhibitory effect of CUEDC2 on NF-κB and JAK1/STAT3 is likely to prevent tumorigenesis, rather than promoting tumor growth." (PMID 26023733, 2015). "Strikingly, all JAK1 LOF mutant tumor organoids had significant resistance to anti-tumor T cell-mediated killing relative to WT controls, with some mutants achieving survival comparable with antibody blockade of MHC-I or growing tumor organoids in the absence of T cells." (PMID 36669486, 2023). "Therefore, we next used this GEMM to determine whether targeting JAK1–2 with ruxolitinib suppresses PanIN progression and mPDAC growth in a GEMM lacking tumor angiogenesis." (PMID 25762644, 2015).